TRPV4 (transient receptor potential cation channel subfamily V member 4)
Diseases named in the same sentence as TRPV4 in open-access papers (continued):
Sharing a sentence is not in itself a finding about the gene and the disease.
autosomal dominant brachyolmia (5 papers, 2015 to 2025). Autosomal dominant brachyolmia is a relatively severe form of brachyolmia, a group of rare genetic skeletal disorders, characterized by short-trunked short stature, platyspondyly and kyphoscoliosis. "Three individuals had mutations in PTPN11 indicating Noonan syndrome, and 1 had a TRPV4 mutation associated with brachyolmia type 3, an autosomal dominant skeletal disorder." (PMID 32939436, 2020). "Autosomal dominant brachyolmia, a milder TRPV4‐associated disorder, actually has the closest fit for the proband's height, with an expected adult range between 160 and 168 cm (or between 5′3′′ and 5′6′′)." (PMID 30693671, 2019). "Activating mutations in transient receptor potential vallinoid family member 4 (TRPV4) leads to a delay in bone mineralization and a spectrum of diseases from autosomal dominant brachyolmia to lethal metatrophic dysplasia." (PMID 26635999, 2015). "Other GSDs share this common disease basis with activating mutations found in different genes causing diverse disorders such as Jansen’s metaphyseal chondrodysplasia (PTH1R), fibrous dysplasia (GNAS,) and brachyolmia type 3 and metatrophic dysplasia (TRPV4)." (PMID 26635999, 2015).
brain injury (5 papers, 2019 to 2023). Acute and chronic (see also brain INJURIES, CHRONIC) injuries to the brain, including the cerebral hemispheres, CEREBELLUM, and brain STEM. "In the pathology of ischemic brain injury, the different and competing roles played by TRPV4 channel activation in the brain can be amply demonstrated." (PMID 37108263, 2023). "TRPV4 protein levels have also been found to increase in the brain I/R model, while TRPV4 selective antagonist HC-067047 attenuates I/R-induced brain injury." (PMID 31636563, 2019).
cerebral edema (5 papers, 2018 to 2026). "In addition, astrocytic TRPV4 channels are key players in the development of cerebral edema, and their role in this process is protective." (PMID 37108263, 2023). "In addition, we have shown that knockout of AQP4 or TRPV4 can cause expression changes of other proteins, specifically glutamate receptors and ion channels, and thus the effect on the development of cerebral edema is not solely due to the specific deletion of these two channels." (PMID 38818517, 2024). "For a closer inspection of the TRPV4 and AQP4 channel complex in the development of brain edema, we applied a real-time iontophoretic method in situ to determine ECS diffusion parameters, namely volume fraction (α) and tortuosity (λ)." (PMID 36568889, 2022). "Although astrocytic TRPV4 channels play a role in oxidative stress and contribute to PID, they may also regulate cell volume and prevent the development of cerebral edema." (PMID 37108263, 2023). "Therefore, the authors believe that the effect of TRPV4 deletion on the extent of cerebral edema was not solely at the level of astrocyte function." (PMID 37108263, 2023). "Nevertheless, brain edema and the metabolism-related change in cerebral blood flow after ICH occur gradually rather than immediately; therefore, we speculated that the significant upregulation of TRPV4 at the hyperacute stage was related primarily to the mechanical stress of hematoma." (PMID 29636662, 2018).
Charcot-Marie-Tooth disease type 2C (5 papers, 2020 to 2025). "Moreover, as will be discussed here, mutations in the ARDs of TRPV4 are associated to genetic diseases such as Charcot-Marie-Tooth disease type 2C." (PMID 32481620, 2020). "TRPV4 c.711A>G and c.1039G>T were reported as VUS for Charcot-Marie-Tooth disease type 2C and TRPV4 c.958C>T as a variant with conflicting interpretations of pathogenicity for skeletal dysplasias, spinal muscular atrophies and Charcot-Marie-Tooth." (PMID 35806193, 2022).
colorectal cancer (5 papers, 2018 to 2024). A primary or metastatic malignant neoplasm that affects the colon or rectum. "The overexpression of some TRP channels in colorectal cancer is related to increased activity of JNK and p38 signaling pathways through TRPM8 or TRPV4 type channels, both associated with calcium entry into the cytoplasm." (PMID 39272835, 2024). "It would be interesting to define the role of endothelial TRPV channels in angiogenesis and carcinogenesis as recent published data implies that TRPV3, TRPV4, TRPV5, TRPM4 and TRPC6 may be thought of as potential genes contributing to colorectal cancer tumorigenesis." (PMID 29914124, 2018).
dysplasia (5 papers, 2011 to 2023). A usually neoplastic transformation of the cell, associated with altered architectural tissue patterns. "This study will improve our understanding of the role of TRPV4 in chondrocyte homeostasis and maturation and lay the foundation for treatment and prevention of TRPV4-mediated dysplasias." (PMID 36810131, 2023).
glioblastoma (5 papers, 2020 to 2025). The most malignant astrocytic tumor (WHO grade IV). "In conclusion, the TRPV4/Cdc42/wasp signaling axis regulates cellular protrusion formation in glioblastoma cells and influences the invasion-growth phenotype of glioblastoma in vivo." (PMID 32843668, 2020). "To test the underlying mechanism of TRPV4 in these processes, we first utilized IF to show the localization of TRPV4 in glioblastoma cells." (PMID 32843668, 2020). "Foremost, TRPV4 inhibitor treatment or downregulation of TRPV4 significantly reduced the invasion-growth of subcutaneously and intracranially transplanted glioblastoma in mice." (PMID 32843668, 2020). "Above results indicated that a strong colocalization and interaction between TRPV4 and F-actin existed in glioblastoma cells." (PMID 32843668, 2020). "TRPV4 promotes glioblastoma progression by accelerating cell invasion and eventually leads to poor prognosis." (PMID 32843668, 2020). "Functionally, stimulation of TRPV4 promoted glioblastoma cell migration and invasion, and repression of TRPV4 hindered the migration and invasion of glioblastoma cells in vitro." (PMID 32843668, 2020). "TRPV4 promotes Rac1 activity in glioblastoma U87 cells leading to increased cell migration through TRPV4-dependent Akt phosphorylation/activation." (PMID 33240883, 2020). "Next, we established an intracranial glioblastoma model by injecting U87 cells at the right striatum of nude mice and detected tumor volume by MRI, and we found that the TRPV4 inhibitor significantly reduced the volumes of tumors compared to the DMSO group." (PMID 32843668, 2020). "Transient receptor potential vanilloid 4 (TRPV4) exhibits a remarkable role in cancer cell motility, but the contribution of TRPV4 to glioblastoma metastasis is not fully understood." (PMID 32843668, 2020). "We reported that TRPV4 interacted with actin and regulated actin arrangement to alter the formation of invadopodia and filopodia in glioblastoma in this study, which is consistent with previous research." (PMID 32843668, 2020). "We first related TRPV4 to the Cdc42/N-wasp pathway in glioblastoma and explored the area of the TRP family with cellular protrusion formation." (PMID 32843668, 2020). "TRPV4 activation in glioblastoma cells is found to promote the activation of Rac1." (PMID 33994356, 2021). "We concluded here that TRPV4 regulates Cdc42/N-wasp axis in glioblastoma cells." (PMID 32843668, 2020). "To test whether the Cdc42 mediates the function of TRPV4 in regulating the invasiveness of glioblastoma, we performed Cdc42 inhibitor to treated U87 cell." (PMID 32843668, 2020). "Notably, two bands of TRPV4 protein were detected in glioblastoma cells by western blot, which implied that TRPV4 protein underwent some modification in glioblastoma cells, such as phosphorylation or ubiquitylation." (PMID 32843668, 2020). "Molecularly, TRPV4 strongly colocalized and interacted with skeletal protein-F-actin at cellular protrusions, and TRPV4 regulated the formation of invadopodia and filopodia in glioblastoma cells." (PMID 32843668, 2020). "In summary, TRPV4 blockade in glioblastoma cells results in decreased invadopodia and filopodia formation and decreased invasion, suggesting that TRPV4 plays a key role in glioblastoma invasiveness." (PMID 32843668, 2020). "To test this hypothesis, we first investigated the migration of glioblastoma cells after treatment with the TRPV4 agonist GSK1016790A (GSK1, 10 nM) or the antagonist GSK2193874 (GSK2, 100 nM)." (PMID 32843668, 2020). "Next, we investigated the function of N-wasp in TRPV4-mediated invasion in glioblastoma." (PMID 32843668, 2020). "Likewise, knockdown of TRPV4 reduced the number of invading cells across the Transwell membrane filter compared to the control in two glioblastoma cell lines." (PMID 32843668, 2020). "Simultaneously, we tested whether TRPV4 could mediate the proliferation and apoptosis of glioblastoma cells." (PMID 32843668, 2020).
glioblastoma (continued). "Thus, Cdc42 is vital for TRPV4-mediated invasion and protrusions formation of glioblastoma." (PMID 32843668, 2020). "Whether TRPV4 contributes to the biology of glioblastoma is undiscovered." (PMID 32843668, 2020). "Thus, we concluded that the promotion of cell invasiveness might be the major reason of TRPV4 upregulation leads to poor prognosis in glioblastoma patients." (PMID 32843668, 2020). "Thus, local Ca2+ signals elicited by these ion channels might promote Ca2+/CaM binding to CaMK II, leading to Akt-mediated Rac1 activation through Tiam1, suggesting participation of TRPV4-mediated Rac1 regulation in glioblastoma progression." (PMID 33240883, 2020). "In glioblastoma cell lines, CBD (30 μM) promoted a lethal mitophagy-mediated arrest by activating TRPV4, which triggered a Ca2+ influx, a fundamental signal for initiating mitophagy." (PMID 40006844, 2025). "In vitro, we detected the expression of TRPV4 in five glioblastoma cell lines (U87, A172, U251, GL261 and C6) and found that TRPV4 was only expressed in U87 and GL261 cells." (PMID 32843668, 2020). "TRPV4 was upregulated in HGG and indicated poor outcomes in glioblastoma patients, which implies that TRPV4 may promote glioblastoma progression." (PMID 32843668, 2020). "However, the TRPV4 antagonist treatment did not change the percentage of Ki-67-positive cells in intracranial glioblastoma tissues, which implied that GSK2 treatment did not affect the proliferation of glioblastoma in vivo." (PMID 32843668, 2020).
intracerebral hemorrhage (5 papers, 2019 to 2023). A cerebrovascular disorder characterized by bleeding into one or both cerebral hemispheres including the basal ganglia and the cerebral cortex. "Activation of TRPV4 channels after intracerebral hemorrhage leads to the destruction of Ca2+ homeostasis, which in turn caused UPR." (PMID 32664312, 2020). "Similarly, a TRPV4 blockade by antagonists in a model of intracerebral hemorrhage preserved the BBB and attenuated neurological deficits." (PMID 36568889, 2022). "According to previous studies, activation of TRPV4 triggers the endoplasmic reticulum stress through increasing [Ca2+]i after intracerebral hemorrhage and blockage of TRPV4 preserves the blood-brain barrier and shows neuroprotection following intracerebral hemorrhage." (PMID 31097691, 2019). "In a mouse model of intracerebral hemorrhage (ICH) induced by intrastriatal injection of collagenase, activation of the TRPV4 channel with a selective agonist GSK1016790A resulted in improved neurological and motor deficits." (PMID 37108263, 2023). "Furthermore, TRPV4 also regulates the integrity of the blood-cerebrospinal fluid barrier and TRPV4 inhibition reduced BBB disruption and consecutive edema in a mouse model of intracerebral hemorrhage and thereby ameliorated neurological symptoms." (PMID 32974355, 2020).
liver cancer (5 papers, 2019 to 2026). An epithelial or non-epithelial malignant neoplasm that arises from the liver. "The high TRPV4 expression in liver cancer has been reported in some patients and the TRPV4 blockade suppresses proliferation and metastasis." (PMID 41562849, 2026). "The prognostic significance of TRPV4 expression in liver cancer is, however, unclear." (PMID 37240443, 2023). "We further verified the increased expression of Sox4, E2f1, Trpv4, and Trim6 in DEN-induced, Srsf3 KO liver cancer tissues by qRT-PCR." (PMID 40568073, 2025). "Although limited studies have shown that TRPV4 participated in cell proliferation in gastric and liver cancer, it has not yet been established whether TRPV4 regulated cell cycle progression to affect cancer cell growth." (PMID 31189890, 2019). "However, the expression pattern of TRPV4 in colon and liver cancer is different from that in nonmelanoma skin cancer." (PMID 31189890, 2019).
liver fibrosis (5 papers, 2014 to 2024). "In the liver, TRPV4 expression was increased in hepatic fibrosis and linked to TGF-β1–induced hepatic stellate cell activation." (PMID 35451372, 2022). "Inhibition of TRPV4 has also been shown to reduce liver fibrosis, a risk factor for HCC." (PMID 32987945, 2020). "To conclude, the upregulation of TRPM7, TRPM8, TRPV3, TRPV4, and TRPC6 is significantly associated with the onset and progression of liver fibrosis." (PMID 37569884, 2023). "Using a mouse model of CCl4-induced liver fibrosis, Fu and colleagues employed the TRPV4 agonist GSK1016790A and inhibitor HC-067,047 in order to activate and inhibit, respectively, TRPV4." (PMID 32987945, 2020). "Their results provide evidence that activation of TRPV4 contributes to the development of liver fibrosis." (PMID 32987945, 2020). "TRPV4 mRNA and protein were measured by RT-PCR and Western blot in patients and rat model of liver fibrosis in vivo and TGF-β1-activated HSC-T6 cells in vitro." (PMID 25013893, 2014). "Second, in order to identify the expression of TRPV4 in the liver tissues from CCl4-treated rats, the severity of liver fibrosis was determined by hematoxylin and eosin (H&E) staining and Masson's trichrome staining." (PMID 25013893, 2014). "TRPV4 immunostaining signal was increased in the liver tissues from liver fibrosis patients compared to the normal liver." (PMID 25013893, 2014). "The findings suggest that TRPV1 may have a protective impact on liver fibrosis, while TRPV4 may contribute to liver damage by facilitating acetaminophen (APAP) metabolism." (PMID 38255767, 2024). "Our results suggested a pathological role of TRPV4 in the activation and proliferation of HSC, indicating that TRPV4 may be a potential therapeutic target in the treatment of liver fibrosis." (PMID 25013893, 2014). "First, we investigated the expression of TRPV4 in the liver tissues from liver fibrosis patients." (PMID 25013893, 2014). "Together, these data suggested that the TRPV4 was induced and may have certain functions in hepatic fibrosis." (PMID 25013893, 2014). "In the context of liver fibrosis, the upregulation of TRPC6, TRPV3, TRPV4, and TRPM7 channels promotes the activation of HSCs and the production and accumulation of ECM components, including α-SMA and COL1A1." (PMID 37569884, 2023). "The TRPV4 channel, a subclass of the TRP superfamily channels, exhibits abnormal expression in liver fibrosis." (PMID 37569884, 2023). "However, the role of TRPV4 in liver fibrosis is largely unknown." (PMID 25013893, 2014). "Furthermore, investigations conducted on a CCl4-induced liver fibrosis mouse model demonstrated that the TRPV4 agonist GSK1016790A exacerbated liver fibrosis, whereas the TRPV4 antagonist HC-067047 effectively ameliorated liver collagen fiber deposition and the degree of liver lobular disorder." (PMID 37569884, 2023). "Thus, TRPV4 may inhibit HSC apoptosis by regulating the activation of the autophagy-dependent AKT signaling pathway, and targeting TRPV4 may become an effective treatment strategy to prevent the progression of liver fibrosis." (PMID 37569884, 2023).
multiple sclerosis (5 papers, 2016 to 2025). A progressive autoimmune disorder affecting the central nervous system resulting in demyelination. "Similar inconsistencies have been observed in TRPV4 research related to multiple sclerosis, where both beneficial and detrimental effects of TRPV4 inhibition on inflammation and myelination have been reported." (PMID 40702215, 2025).
myocardial ischemia (5 papers, 2016 to 2021). A disorder of cardiac function caused by insufficient blood flow to the muscle tissue of the heart. "Ca2+ entry via the transient receptor potential vanilloid 4 (TRPV4) channel contributes to Ca2+ overload and triggers many pathophysiological conditions, including myocardial ischemia/reperfusion (I/R) injury." (PMID 31636563, 2019). "Transient receptor potential vanilloid 4 (TRPV4) is highly expressed in heart and vessels and can be activated during myocardial ischemia/reperfusion (I/R)." (PMID 28542130, 2017). "Our unpublished data show that inhibition of TRPV4 reduces infarction in a myocardial ischemia-reperfusion model through inhibition of ROS production (Du and Chen, unpublished data)." (PMID 27799895, 2016). "The first study to demonstrate a critical role for TRPV4 in mediating myocardial ischemia/reperfusion (I/R) injury was performed in mice with left anterior descending (LAD) coronary artery ligation, in the presence and absence of TRPV4-specific inhibitor HC067047." (PMID 34867442, 2021).
neuropathic pain (5 papers, 2014 to 2024). Chronic pain caused by damage to nerve fibers. "RN-1734, another TRPV4 antagonist, also prevented the sensitization of TRPV4 and attenuated paclitaxel-induced neuropathic pain." (PMID 38730655, 2024). "Then, TRPV4 could be a promising pharmacological strategy to control pain observed in neuropathic pain models, especially mechanical allodynia and thermal hyperalgesia." (PMID 36670886, 2022). "Consequently, these channels contribute to the TRPV4 detection of mechanical nociceptive stimuli in sensitized primary afferent nociceptors in the paclitaxel-induced neuropathic pain model." (PMID 36670886, 2022).
ocular hypertension (5 papers, 2016 to 2025). Abnormally high intraocular pressure. "This study establishes a mechanistic framework that integrates biochemical and biomechanical risk factors of POAG and highlights the pivotal role of TRPV4, a polymodal Ca2+-permeable channel, as a key regulator of TM contractility and ocular hypertension." (PMID 39574569, 2025). "TRPV4 activation is necessary to maintain LV-TGFβ2-induced ocular hypertension (OHT)." (PMID 40552711, 2025). "Thus, TRPV4 is a potential IOP sensor within the conventional outflow pathway and a novel target for treating ocular hypertension." (PMID 27510430, 2016).
spinal muscular atrophy (5 papers, 2018 to 2025). A motor neuron disease that affect the muscles, and characterized by muscle weakness and atrophy resulting from progressive degeneration and irreversible loss of the anterior horn cells in the spinal cord (i.e., lower motor neurons) and the brain stem nuclei. "Patients with Spinal Muscular Atrophy have several mutations in TRPV4, namely at R316C and R269H." (PMID 35813831, 2022). "Mutations in TRPV4 cause many genetic disorders, such as Charcot–Marie–Tooth disease and spinal muscular atrophy, due to dysregulated activation of TRPV4." (PMID 29690581, 2018).